ERBB3 (erb-b2 receptor tyrosine kinase 3)
Diseases named in the same sentence as ERBB3 in open-access papers (continued):
Sharing a sentence is not in itself a finding about the gene and the disease.
tumor (continued). "Thus, inhibition of ErbB3 signaling had a profound effect on growth of this HER2 overexpressing tumor." (PMID 37316561, 2023). "Interestingly, among the 21 tumor samples analyzed, 6 had Her-2 and/or ErbB3 alterations and the 5 patients with clinical benefit belonged to this group, whereas 15 out of 15 patients without ErbB alterations had progressive disease as best response." (PMID 36293515, 2022). "In vivo studies suggest that the high ErbB3 expression correlates with a larger tumor volume and might lead to the failure of both hormonal and tyrosine kinase inhibitor-based anti-tumor therapies." (PMID 35337112, 2022). "Profiling of phosphorylated ERBB2 and ERBB3 in end-stage tumors indicated that on-target activity of AF was sustained despite tumor progression, pointing to the emergence of alternative resistance mechanisms that could in the future be explored further." (PMID 36355420, 2022). "Whether other kinases, such as MST1R, ERBB3, etc., have an impact on the anti-tumor effect of oncolytic viruses remains to be further studied by other members of the team." (PMID 35401439, 2022). "However, recent evidence supports the key role of ERBB3 in cell transformation and tumor malignancy." (PMID 35581263, 2022). "Moreover, we confirmed the mutation in ARID1A gene (p.R1276∗), ERBB3 (p.S128R), KEAP1 (p.R135H), PALB2 (p.P807S), and NTRK1 (p.Q736X), previously reported by F1CDx, both in the tumor and in the ccfDNAs." (PMID 34178989, 2021). "Additionally, some transmembrane ErbB3 is directly cleaved, forming a cytoplasmic stable and active 80 kDa form, which effects are normally offset by the tumour suppressor p14ARF sequestering the 80 kDa form for degradation." (PMID 34274969, 2021). "Molecular profiling implicated EGFR as a likely mediator of enhanced tumor growth in the absence of ERBB3." (PMID 34843459, 2021). "HER3 (ErbB3), which had long been neglected, has emerged as a key oncogene, regulating the activity of other receptors and being involved in progression and tumor escape in multiple types of cancer." (PMID 34196609, 2021). "However, ErbB3 downregulation (e.g. by siRNA) can restore tumour responsiveness to various therapeutic approaches, including TKIs, potentially of clinical relevance for this family." (PMID 34274969, 2021). "ERBB3 plays an important role in cancer, and the mutation of ERBB is a potential tumor driver." (PMID 33828969, 2021). "Finally, hsa-miR-145 acts as a tumor suppressor through the inhibition of different proteins like ERBB3 and RTKN." (PMID 32635415, 2020). "Moreover, chemotherapies have been shown to increase expression of both IGF-1R and ErbB3 in tumor cell lines, rendering these resistant to cytotoxic therapies." (PMID 31728045, 2019). "Therefore, targeted therapy inhibits the interaction between ErbB1 and ErbB3 and can be more effective in eradication of tumor progression." (PMID 30621788, 2019). "Thus inhibition of ErbB3 on macrophages blocked the ability of macrophages to enhance tumor cell transmigration." (PMID 29636067, 2018). "Past studies have focused on characterizing ErbB3 expression of tumor cells, but our experiments suggest that JAG1 and ErbB3 expression on macrophages may also play an important role." (PMID 29636067, 2018). "To determine if seribantumab is inhibiting tumor growth by the intended mechanism, we collected tumors from the dose-ranging mouse xenograft study and measured both total and phosphorylated levels of ErbB3 by ELISA." (PMID 28725482, 2017). "One group of researchers who worked with 17DMAG (a water-soluble inhibitor of the Hsp90 activity) proposed to designate ErbB3 as such a biomarker: they asserted that if ErbB3 is expressed by tumor cells, these cells cannot be sensitized to radiation by means of Hsp90 inactivation." (PMID 28291803, 2017).
tumor (continued). "Because seribantumab is designed to block ErbB3 signaling, we only expect it to be effective in cancers in which a substantial proportion of cancer cells with active signaling persists within a heterogeneous tumor." (PMID 28725482, 2017). "Furthermore, the carriers of T genotype was related to the significantly high expression of ErbB3, and to big tumor size, poor differentiation as well as the high probability of metastasis." (PMID 28924391, 2017). "ERBB3 is upregulated in a number of human cancers such breast, colon, gastric, ovarian and prostate but seldom reported in veterinary cancers although it would appear the instrumental role that ERBB3 may play in some veterinary tumours is yet to be elucidated." (PMID 28591206, 2017). "The strong association between ERBB2 and ERBB3 overexpression in Uro and GU HER-positive cases, but not in the Basal/SCC-like HER2-positive cases, should also be considered, as ERBB3 has been shown to be essential for ERBB2 driven tumor formation and maintenance." (PMID 28388586, 2017). "Thus, studies to capture ERBB3 expressing cells in cancers will improve our understanding of the roles of ERBB3-mediated tumor progression and metastasis." (PMID 29321816, 2017). "Consistent with the findings of other groups, we could recently identify two distinct breast cancer populations that expressed either high (~60% of tumours) or low (~40% of tumours) levels of ErbB3." (PMID 28417948, 2017). "Thus, we conclude that both routes to PI3K activation, emanating from ErbB2/Grb2/RAS and ErbB3, must be interrupted to achieve full anti-tumour response." (PMID 27255951, 2016). "We first investigated the expression of ErbB3 on normal or tumour prostate tissues." (PMID 27191720, 2016). "In stark contrast to these findings, no ERBB3 activating mutation was found in any of the 55 tumor samples." (PMID 27602491, 2016). "Combinatorial therapies including ErbB3 targeting may ameliorate tumor responses to anti-EGFR therapies." (PMID 27609096, 2016). "We first assessed ErbB3 expression in normal and tumour prostate tissues." (PMID 27191720, 2016). "We also provided evidences that the mechanism underlying the synergistic interaction between the two classes of agents is related to the downregulation of EGFR and ErBB2 and to the differential modulation of ErbB3 based on tumor cell phenotype, epithelial vs mesenchymal, induced by the HDACis." (PMID 26862736, 2016). "The nuclear localization of ErbB3 has been reported in various cancer tissues and cell lines but the nuclear functions and the putative correlation with tumour progression and resistance to therapy remain unclear." (PMID 27191720, 2016). "Although either downregulation of EGFR and ErbB2 or increased ErbB3 expression upon treatment with HDACi have been reported before in tumor cells and particularly in NSCLC cell lines, to our knowledge this is the first study reporting these effects in primary cultures." (PMID 26862736, 2016). "Next, phosphorylation of ErbB3 in tumor xenografts was assessed." (PMID 27609096, 2016). "Importantly, the EGFR-ErbB3 interdependency has been observed not only in tumor cells harbouring mutationally activated EGFR, but also in tumors with wild-type EGFR, revealing a role for ErbB3 that extends beyond the context of mutationally activated EGFR." (PMID 26862736, 2016). "Indeed, as devoid of extracellular ligand-binding domain, ErbB380kDa is untargeted by ErbB3 therapeutic antibodies currently under Phase I or II clinical assays in various tumours, we have tested so far (unpublished data)." (PMID 27191720, 2016). "Moreover, the expression of ERBB2 and ERBB3 alone or in combination with resistance markers seem to promote uncontrolled tumor cell growth in overt metastases, leading to a shorter OS." (PMID 27223437, 2016). "The presence of cells that co-expressed EPHB2 and ERBB3 was rare (2.1% tumour cells)." (PMID 26367378, 2015).
tumor (continued). "ERBB3 was predominantly localised to the apical and basolateral cell surface of normal intestinal epithelial cells and was detected at the cell surface in the majority of tumours with some diffuse cytoplasmic staining apparent in a few cases." (PMID 26367378, 2015). "A similar mechanism was observed in vivo where ERBB3 knockdown delayed tumour growth." (PMID 26367378, 2015). "It is not clear whether same mechanisms are utilized to simultaneously upregulate both erbB2 and erbB3, or whether tumor cells first overexpress one receptor which subsequently enhances expression of the other receptor." (PMID 24886126, 2014). "Identifying other mediators of erbB3 signaling may provide additional opportunities to develop novel strategies revoking drug resistance and tumor metastasis." (PMID 24886126, 2014). "Furthermore, the biological consequences of the targeting of ERBB3 by miR-143/145 were examined by cell proliferation and invasion assays in vitro and by the mouse xenograft tumor model in vivo." (PMID 25248370, 2014). "In tumor cells, integrin β4 can relocate from hemiodesmosomes to the leading edge of migrating cells where it is involved in the signaling of many receptor tyrosine kinases, including ErbB2, ErbB3, EGFR and Met." (PMID 24885350, 2014). "Taken together, our results not only reveal a critical role for miR-143 and miR-145 as tumor suppressors in breast carcinogenesis through repression of ERBB3 translation but also show that different miRNAs within a cluster can simultaneously and cooperatively repress a given target mRNA." (PMID 25248370, 2014). "It is conceivable to hypothesize that novel approaches against HRG, such as neutralization Abs, may exert similar anti-tumor efficacy as therapeutic targeting of erbB3." (PMID 24886126, 2014). "ERBB3 show several similarities to ALK, encoding the NB familial gene, and thus made a good candidate gene with potential role in the tumour development of r4 tumour types." (PMID 23835063, 2013). "Furthermore, combination of anti-ErbB3 antibodies with EGFR TKIs synergistically affect cell proliferation in vitro, cause cell cycle arrest, up-regulate p21 expression and inhibit tumor growth in mouse xenografts." (PMID 23896512, 2013). "In addition, the erbB3 inhibitors based on a novel biologic scaffold termed a surrobody have been developed and show inhibitory effects on tumor cell proliferation in vitro and in vivo." (PMID 24215614, 2013). "Nonetheless, the remaining tumor cells expressed similar levels of erbB2 and erbB3." (PMID 24168763, 2013). "Only one of the NB tumours (case 9) showed a strong ErbB3 signal." (PMID 23835063, 2013). "However, several studies have established that the ErbB2/ErbB3 heterodimer functions as an oncogenic unit in ErbB2 amplified tumour cells." (PMID 23202898, 2012). "ErbB3 has been disregarded for several years as a cancer target, although the elevated expression of this receptor in several human cancers led in early times to postulate its involvement in tumor progression." (PMID 22889873, 2012). "Co-expression of ErbB3 with other ErbB family members was indicative of tumor recurrence." (PMID 22889873, 2012). "Indeed it has been shown that both in tumors resistant to trastuzumab or in tumor resistant to gefitinib, ErbB3 is upregulated and, most importantly pErbB3 is constitutively activated." (PMID 22889873, 2012). "In OVCAR8 xenograft mouse model, down-regulation of ErbB3 by RNAi decreased tumor progression compared to controls, in the same mouse model treatment with a monoclonal anti-ErbB3 antibody also resulted in inhibition of tumour progression." (PMID 22889873, 2012).
tumor (continued). "At the cellular level, a weak level of ErbB3 activity may be sufficient to induce drug resistance in the context of an ErbB signaling-dependent tumor cell." (PMID 21701703, 2011). "Given the pivotal roles of these ERBB3 downstream molecules in regulating tumor growth and angiogenesis, these results indicate that miR-148 may inhibit tumor angiogenesis via targeting ERBB3 and its downstream molecules." (PMID 23554686, 2011). "Interestingly, total membrane and cytoplasmic erbB3 expression was significantly higher in phosphorylated membrane IRS-1 Y612-positive tumours than in phosphorylated membrane IRS-1 Y612-negative tumours (P = 0.009 (n = 33))." (PMID 21939528, 2011). "Additional findings from our laboratory also point to the lack of activating mutations in EGFR and ErbB3 genes, giving further strength to ligand-driven tumour cell proliferation as a paramount tumourigenic mechanism within the PDAC microenvironment." (PMID 21792199, 2011). "While increased levels of EGFR and ErbB3 protein could be detected in the bitransgenic tumours when compared with normal tissue, the extent of the increase was dramatically reduced compared with that observed in the c-ErbB2 tumours." (PMID 18700973, 2008). "The reciprocal positive regulation of Src by ErbB2 and ErbB2 by Src is strongly diminished in the bitransgenic tumours (in addition to the reduced activation of ErbB3) indicating a general decline in plasma membrane tyrosine kinase signalling in the bitransgenic tumours." (PMID 18700973, 2008). "Radioiodinated ALM (125I-ALM) accumulated to similar levels (P=0.59) in two different ErbB2‘+’/ErbB3‘+’ tumour xenografts; 125I-ALM accumulated in BT-474 and SK-OV-3 tumour xenografts at 2.89±0.2 and 3.07±0.27% injected dose per gram of tissue (% ID per g), respectively, by 24 h post-injection." (PMID 18841159, 2008). "However, ErbB2‘+’/ErbB3‘+’ normal cells are predicted to be in vast excess compared with tumour cells in vivo." (PMID 18841159, 2008). "Furthermore, the involvement of ErbB-3 in tumor progression was also supported by the finding that its depletion, in the absence of hormone stimuli, induces apoptosis, inhibits the in vitro invasion and favors TAM responsiveness." (PMID 18270579, 2008). "However, in agreement with our data, it has been found that the DFS is shorter in patients with ErbB-3 overexpression and that the level of ErbB-3 expression in primary BC seems to be involved in tumor progression from non-invasive to invasive tumors." (PMID 18270579, 2008). "Despite the fact that ALM was retained in the ErbB2‘+’/ErbB3‘−’ MVM2 tumours at statistically greater levels than seen in blood (0.98±0.09 vs 0.28±0.04 %ID/g; P<0.001), the levels of targeting were significantly lower than those seen in either the BT-474 or SK-OV-3 xenograft models (P<0.001)." (PMID 18841159, 2008). "The majority of tumor-derived cell lines expressed moderate to high levels of both erbB3 and erbB2." (PMID 16168116, 2005). "For instance, elevated IL11 expression may suppress anti-tumor immune activity by fostering the development of an immunosuppressive microenvironment, while increased ERBB3 expression may impact immunotherapy outcomes by modulating the interplay between tumor cells and immune cells." (PMID 40708839, 2025). "Third, NRG1 is a non-selective agonist of the ERBB system, binding to both ERBB3 and ERBB4 receptors, and thus it may activate ERBB3 receptors in ERBB2-overexpressing tumor cells, thereby enhancing the formation of ERBB3/ERBB2 complexes, which could induce or accelerate cancer growth." (PMID 39794341, 2025). "Furthermore, metabolites secreted by Lactobacillus casei, Lactobacillus paracasei, Lactobacillus rhamnosus, and Lactobacillus plantarum have been found to inhibit the expression of ErbB-2 and ErbB-3 genes, which subsequently decreases tumor proliferation mediated by these receptors." (PMID 39948481, 2025).
tumor (continued). "In addition, inactivation of ERBB3 in cancer cells attenuates tumor growth and angiogenesis." (PMID 38957319, 2024). "From these results we learned that modulation of ErbB3 localization influenced dimer formation with consequences for downstream target activation in HSPC vs CRPC cell lines which might impact tumor cell proliferation (ERK signalling) and survival (AKT signalling)." (PMID 39257973, 2024). "The ErbB3 atypical expression in MM may have potential effects on tumor cell growth or survival." (PMID 38410384, 2024). "It deserves notice, however, that there were still a few cases with identified variants from ctDNA only, such as ERBB3 mutations, and these patients should be followed up longitudinally to understand the meaning and prognosis of the ctDNA-positive/tumor-tissue-negative phenomenon." (PMID 37760445, 2023). "Notably, in the invasive tumors caused by ERBB2 and ERBB3, THE insulin-like growth factor 2 (IGF2) and insulin-like growth factor binding protein 5 (IGFBP-5) are highly expressed, and these growth factors are very important for tumor growth." (PMID 35990843, 2022). "MEK/Erk and PI3K/Akt could also be activated by different growth factors, such as EGFR and ErbB3, thus tumor types and stages, as well as CD44 isoforms and expression levels should be considered when these inhibitors are combined with chemotherapy for PDAC treatment." (PMID 35931675, 2022). "The modulation of the nucleolar ErbB3 could pave the way towards potential anti-cancer backup strategies and could represent a possible novel pharmacological approach to counteract cell proliferation in tumours." (PMID 35255831, 2022). "Additionally, ERBB3-targeting antibodies are now entering clinical trial for other indications (e.g. seribantumab for NRG1-fusion harboring tumours) (NCT04383210), which may provide further options for clinical investigation of this treatment concept." (PMID 35501832, 2022). "MiR-323a-3p, a tumor suppressor, could target both ErbB3 and EGFR directly." (PMID 35319011, 2022). "Elevated mutation burden, observed in 32% (8/25) of tumors, was associated with systemic activation of HER3 (ERBB3) signaling, which may represent a potential therapeutic target for patients who have progressed following immunotherapy and/or whose tumor demonstrates high mutation burden." (PMID 33826614, 2021). "Sanger sequencing of tumour DNA excluded homozygosity of the ERBB3 variant (data not shown)." (PMID 34274969, 2021). "Another reason for the low tumor-plasma concordance in our study may be the too low VAF of the mutations identified in tumors for some genes (e.g., MTOR, PIK3CA, ERBB3, and RAF1), raising the question of whether they are driver mutations or just passenger variants." (PMID 34356096, 2021). "However, immunohistochemistry results indicate that lack of ERBB3 signaling primarily contributes to tumor growth by increasing cell proliferation as shown in an increase in Ki67 positive cells in ERBB3-deficient polyps." (PMID 34843459, 2021). "Therefore, as an EGFR-driven tumor, the role of ErbB3 in HNSCC is somewhat unclear." (PMID 29305574, 2018). "Therefore, we considered that the potent anti-tumor effect exerted by the ErbB3 antibody observed in vivo may also be related to a specific requirement for ErbB3 in tumor growth under hypoxic conditions." (PMID 29305574, 2018). "However, our study indicated that mIR-211 as a tumor suppressor in human GC by targeting ErbB3." (PMID 28924391, 2017). "The high prevalence of NRG1 expression in HNSCC, while necessary for full ErbB3 activation, may be insufficient to fully predict the anti-tumor activity of an ErbB3-blocking antibody and may explain why the clinical studies to date for anti-ErbB3 antibodies have not proven successful." (PMID 28723928, 2017).